RN7SL220P (RNA, 7SL, cytoplasmic 220, pseudogene)
Gene: Miscellaneous RNA gene on chromosome 10 (68,007,718 to 68,008,017, reverse strand). Ensembl gene ENSG00000266467.
Homologues: Orthologues: chimpanzee Metazoa_SRP (99% identical), macaque Metazoa_SRP (94% identical). Paralogues in human: RN7SL1 (87% identical), RN7SL2 (87% identical), RN7SL3 (87% identical), RN7SL122P (84% identical), RN7SL127P (84% identical), RN7SL769P (83% identical), RN7SL448P (83% identical), RN7SL566P (83% identical), RN7SL126P (83% identical), RN7SL478P (83% identical), RN7SL493P (83% identical), RN7SL559P (83% identical), and 705 more.